PER1 (period circadian regulator 1)
Diseases named in the same sentence as PER1 in open-access papers (continued):
Sharing a sentence is not in itself a finding about the gene and the disease.
metabolic disorders (4 papers, 2019 to 2025). "In metabolic disorders, PER1 modulates endocrine function, glucose-lipid metabolism, and energy balance." (PMID 41451215, 2025). "In metabolic disorders, PER1 modulates endocrine function, glucose and lipid metabolism, as well as energy balance." (PMID 41451215, 2025). "This review summarizes the biological characteristics and regulatory mechanisms of PER1, as well as its roles and molecular mechanisms in cardiovascular diseases, nervous system diseases, metabolic disorders, immune-related diseases, and tumors." (PMID 41451215, 2025). "Feeding only during the daytime in animals was also described to lead to metabolic disorders and disrupted rhythm in the expression of Per1 and Per2 mRNA in the perifornical area and the arcuate nucleus of the hypothalamus." (PMID 31139215, 2019).
neurodegenerative disease (3 papers, 2022 to 2025). A disorder of the central nervous system characterized by gradual and progressive loss of neural tissue and neurologic function. "In the nervous system, PER1 regulates ischemic brain injury, sleep homeostasis, and associates with neurodegenerative diseases." (PMID 41451215, 2025). "In degenerative diseases, changes in PER1 expression are not only associated with specific disorders but also broadly involved in regulating behavior, memory, and neural functions." (PMID 41451215, 2025). "In mouse glial cells, knockdown of the PER1 gene leads to increased β42 deposition and expression of misfolded proteins during senescence, suggesting an association between PER1 and neurodegenerative diseases." (PMID 39267721, 2024). "Several regulated genes, such as Arpc3, Glp2r, Sirt3 and Per1 have been reported to exert protective effects in neurodegenerative diseases or reverse memory deficits in various models, underlining the observed protective effects of spermidine." (PMID 35780157, 2022).
cardiovascular diseases (1 paper, 2025). "In cardiovascular diseases, PER1 helps regulate blood pressure, renal function, and vascular inflammation." (PMID 41451215, 2025). "In cardiovascular diseases, PER1 regulates blood pressure and renal function, and is involved in the anti-inflammatory mechanism of vascular injury." (PMID 41451215, 2025). "Regulatory directions and mechanisms of action of PER1 in cardiovascular diseases." (PMID 41451215, 2025).
colorectal (1 paper, 2021). "In our study cohort, we found a significant underexpression of PER1/2/3, CRY1/2 and NR1D1 proteins in CRC versus normal tissue, indicating an important role of these genes in colorectal carcinogenesis." (PMID 34440171, 2021).
endocrine neoplasms (1 paper, 2022). "PER1 is the most common clock gene that is implicated in the endocrine neoplasms; in most cases, their expression is downregulated in tumoral compared to normal tissues, including in HCC." (PMID 35993051, 2022).
nervous system diseases (1 paper, 2025). "Regulatory pathways/molecules, specific mechanisms of PER1 in neurological diseases." (PMID 41451215, 2025). "PER1 exerts a pivotal role in neurological disorders, including ischemic brain injury, sleep homeostasis, and degenerative neuropathies, through multiple regulatory pathways such as circadian rhythm modulation, cell autophagy, oxidative stress, cellular apoptosis, and neurotransmitter systems." (PMID 41451215, 2025).
vascular disorder (1 paper, 2025). A general term used to describe any disease affecting blood vessels]. "Alterations of CLOCK, Bmal1, PER1, and PER2 has been observed in the placental cells of pregnant women with vascular disorders like pre-eclampsia." (PMID 40137423, 2025).
PER1 also shares sentences with these, for which no sentence is quoted: mental illness (3 papers); bladder cancer (2); brain glioma (2); Cluster headache (2); delirium (2); injury (2); pancreatic ductal adenocarcinoma (2); rheumatoid arthritis (2); steatosis (2); triple-negative breast carcinoma (2); uveitis (2); abortion (1); alcoholism (1); alopecia (1); androgen excess (1); apnea of (1); atopic dermatitis (1); cardiac hypertrophy (1); cardiomyopathy (1); cataract (1); cerebral small vessel disease (1); colorectal tumors (1); coronary heart disease (1); COVID-19 (1); familial breast cancer (1); fibrosarcoma (1); fragile X syndrome (1); gingival cancer (1); glioblastoma (1); haemorrhagic stroke (1).
A further 36 diseases each share a sentence with PER1 in 1 paper.